FUBP1 (far upstream element binding protein 1)
Diseases named in the same sentence as FUBP1 in open-access papers (continued):
Sharing a sentence is not in itself a finding about the gene and the disease.
COVID-19 (2 papers, 2022 to 2023). A disease caused by infection with severe acute respiratory syndrome coronavirus 2. "Combining risk genes from the HGI with RBPs, we identify two COVID-19 risk loci that regulate the expression levels of FUBP1 and RAB2A in the lung." (PMID 37932299, 2023). "Although little is known about the function of FUBP1 in COVID-19, evidence has shown that FUBP1 suppresses protein translation of Japanese encephalitis virus (JEV) by targeting its 5’ and 3’ UTR61." (PMID 37932299, 2023). "It is promising to target FUBP1 in the treatment of COVID-19 since a study has found that FUBP1 was repressed after SARS-CoV-2 infection in Calu-3 cells, and expression of FUBP1 could be reversed after allicin exposure to SARS-CoV-2-infected cells." (PMID 37932299, 2023). "Further studies such as CRISPR are needed to clarify in which process the anti-viral role of FUBP1 and the pro-viral role of RAB2A play in COVID-19." (PMID 37932299, 2023). "Even though few potential drugs have been found to target FUBP1 and RAB2A, using RNA-binding proteins to treat COVID-19 is still promising." (PMID 37932299, 2023). "Seven common DEGs (PPARGC1A, FUBP1, ITGB8, SYCP2, RSAD2, FGF1, and FERMT1) were identified from the GSE164805 dataset of patients with mild COVID-19, and the GSE50395 dataset from APS patients." (PMID 36241659, 2022). "The results showed that FUBP1 and RAB2A are expressed in several types of nasopharyngeal epithelial cells, including FOXN4+ cells, squamous cells, ciliated cells, and secretory cells, in the upper respiratory tract of COVID-19 patients, especially the vRNA+ group." (PMID 37932299, 2023).
esophageal squamous cell carcinoma (2 papers, 2018 to 2021). Esophageal squamous cell carcinoma (ESCC) is a type of esophageal carcinoma (EC) that can affect any part of the esophagus, but is usually located in the upper or middle third. "Overexpression of alternative splicing of far upstream element binding protein 1 (FUBP1) interacting repressor (FIR; poly(U) binding splicing factor 60 [PUF60]) and cyclin E were detected in esophageal squamous cell carcinomas (ESCC)." (PMID 29796163, 2018). "FUBP1 stimulates c-MYC expression in esophageal squamous cell carcinoma (ESCC) and facilitates ESCC development." (PMID 34116677, 2021).
sarcoma (2 papers, 2022). A usually aggressive malignant neoplasm of the soft tissue or bone. "For example, FUBP1 is positively correlated with overall survival in patients with sarcoma." (PMID 35274005, 2022). "OS analysis data demonstrated that high FUBP1 expression was significantly correlated with poor prognosis in ACC, KICH, LUAD, SARC (sarcoma) (p < 0.05), and LIHC (p < 0.001)." (PMID 35274005, 2022).
anaplastic gliomas (1 paper, 2016). "In a different study, anaplastic gliomas were classified based on ATRX, CIC, FUBP1 and IDH status and patients with ATRX and IDH mutated tumors showed a significantly longer overall survival compared to patients with mutated IDH and wild type ATRX tumors." (PMID 27311324, 2016).
brain tumors (1 paper, 2012). "Sequencing analysis of CIC and FUBP1 genes in the same brain tumors revealed 29 and 16 somatic mutations, respectively." (PMID 22869205, 2012).
cervical squamous cell carcinoma (1 paper, 2022). A squamous cell carcinoma arising from the cervical epithelium. "Regarding DFS, high FUBP1 expression conferred a short survival time in ACC (p < 0.001), CESC (cervical squamous cell carcinoma and endocervical adenocarcinoma), LUSC (p < 0.01), and KICH (p < 0.05)." (PMID 35274005, 2022).
heart tumors (1 paper, 2024).
intestinal cancer (1 paper, 2021). "Mutations in the FUBP1 gene and loss of function are frequently found in patients with central nervous system diseases and intestinal cancer." (PMID 34116677, 2021).
lymph node metastasis (1 paper, 2021). "In addition, correlation analysis demonstrated that elevated FUBP1 positively associated with lymph node metastasis and advanced clinical stages in CRC." (PMID 34288405, 2021).
mesothelioma (1 paper, 2022). A usually malignant and aggressive neoplasm of the mesothelium which is often associated with exposure to asbestos. "In contrast, low FUBP1 expression was related to poor prognosis for MESO (mesothelioma), and READ (rectum adenocarcinoma) patients, according to overall survival, as well as SKCM patients (p < 0.05), according to DFS." (PMID 35274005, 2022).
osteoporosis (1 paper, 2025). A condition of reduced bone mass, with decreased cortical thickness and a decrease in the number and size of the trabeculae of cancellous bone (but normal chemical composition), resulting in increased fracture incidence. "CSRP2 and FUBP1 can serve as biomarkers for the early prediction of osteoporosis risk in individuals with low BMD/PBM." (PMID 40927289, 2025). "CSRP2 and FUBP1 can serve as biomarkers for the early prediction of osteoporosis risk in individuals with low peak bone mass or bone mineral density." (PMID 40927289, 2025).
tumor (67 papers, 2012 to 2025). "Given that Fubp1 is implicated in tumor development, we validated the role of Fubp1 in cell cycling in this study." (PMID 32481602, 2020). "Then, the NB transcriptome microarray from the GEO database was re-analysed and showed that the tumour-associated transcription factor FUBP1 was significantly increased with NB malignancy." (PMID 31511046, 2019). "FUBP1 mRNA expression was markedly associated with tumor size (P = 0.0294) and TNM stage (P = 0.0101)." (PMID 28076379, 2017). "In the absence of these mutations and a complete analysis of the exome sequencing, one possibility is that it is the combination of CIC and FUBP1 mutations that provide this tumor with an advantage during engraftment." (PMID 23527265, 2013). "Collectively, we identified that 1p loss decreased FUBP1 protein expression, which was associated with down-regulation of ribosome biogenesis and translation processes, and ultimately with weakened tumor proliferation and a favorable outcome for patients with CDC." (PMID 40917497, 2025). "In addition to well-established cancer drivers, they showed that loss of FUBP1 drives transformation and promotes tumour growth when PTEN is also lost." (PMID 40650785, 2025). "The recent inclusion of the FUBP1 gene in the “long-tail driver” category of the less-frequently mutated genes due to its alternative splicing regulatory role in several oncogenes and tumor suppressors, makes it a very attractive therapeutic target." (PMID 35158934, 2022). "Moreover, both the correlation between the expression of FUBP1 and tumor mutational burden (TMB) and microsatellite instability (MSI) were investigated across all cancers in TCGA." (PMID 35274005, 2022). "Whether FUBP1 is associated with NRP1 expression in tumor-infiltrated lymphocytes remains more discussion." (PMID 33987449, 2021). "Given that a tumor is basically caused by uncontrolled cell cycle progression, it is not surprising that the cell cycle inhibitor p21 is another main target gene repressed by FUBP1." (PMID 32481602, 2020). "High levels of FUBP1 mRNA expression were associated with higher tumor stage and tumor size." (PMID 28076379, 2017). "This suggests that mutations in CIC and FUBP1 may have a weaker effect on tumor progression." (PMID 37533228, 2023). "FUBP1 mutation may provide a survival advantage to tumor cells." (PMID 37533228, 2023). "CRC recurrence and distant metastasis arise from a subpopulation of CSCs, and FUBP1 expression was negatively associated with tumor differentiation status, which implied that cell migration and invasion enhanced by FUBP1 might be attributed to the regulation of stemness." (PMID 34288405, 2021). "FUBP1 mutation was seen in six out of the twelve recurrent tumors; such mutation was acquired in recurrent tumors in 2 cases (patients 2 and 11), and the same FUBP1 mutation as that in the primary tumor was retained in the recurrent tumor in 4 cases (patients 5, 8, 10, and 12)." (PMID 28270234, 2017). "However, our findings contradicted a study, which reported that the expression levels of FUBP1 protein and the clinicopathological characteristics were not correlated despite the highly significant association between high levels of FUBP1 protein and high tumor cell proliferation rates (ki-67)." (PMID 28076379, 2017). "FUBP1 was overexpressed in various tumor types and plays a role in cell proliferation, cell migration and invasion, and cell apoptosis." (PMID 40565351, 2025). "Proliferation, and cytokine release and TCRB repertoire of from PDA patient peripheral T lymphocytes, before and after CT, were analyzed in vitro in response to four tumor-associated antigens (TAA), namely ENO1, FUBP1, GAPDH and K2C8." (PMID 39176093, 2024). "Together, these data demonstrate that this competitive peptide effectively prevents FUBP1 methylation and inhibits tumor growth." (PMID 39146021, 2024).
tumor (continued). "FUBP1 depletion curtailed xenograft growth, whereas reintroducing FUBP1 robustly accelerated xenograft growth, as determined by tumor weight and volume." (PMID 39146021, 2024). "A significant reduction in tumor weights was observed in FUBP1 knockdown xenografts upon lobaplatin treatment compared with the tumors of control mice inoculated with vector control shRNA." (PMID 37180822, 2023). "Considering the head body of the pancreas as the tumor site, a slight relationship of both FUBP1 and ENO1 aAb titer with the prognosis was observed." (PMID 37910256, 2023). "When complexed with the far upstream element (FUSE) site that negatively regulates c-Myc expression, FUBP1 promotes tumor growth and glycolysis of cancer cells." (PMID 37910256, 2023). "FUBP1 was identified as a long tail cancer driver and widespread regulator of oncogene alternative splicing and tumor suppressor." (PMID 37180822, 2023). "Tumor cells were then cotransfected with small interfering oligonucleotides targeting FUBP1 and PTGES‐overexpression plasmids, and these tumor cells demonstrated increased cell viability compared with cells transfected with only FUBP1 knockdown nucleotides." (PMID 37180822, 2023). "The MG63 tumor volumes in the FUBP1‐overexpressing mice were significantly larger than those in the vector‐overexpressing mice after lobaplatin treatment." (PMID 37180822, 2023). "Patient 63 acquired subclonal mutations in FUBP1:p.I271Rfs*3 and BCOR:p.D1355N when tumor recurrence was observed." (PMID 37533228, 2023). "With the TCGA and GTEx data, the expression of FUBP1 in tumor tissues and adjacent normal tissues was further analyzed." (PMID 35274005, 2022). "The expression of FUBP1 was found to be negatively correlated with the infiltration of CD8+ T lymphocytes in GBM, HNSC-HPV- and UCEC but positively correlated with that of tumor-associated fibroblasts in CESC, ESCA, HNSC, LIHC, LUAD, PAAD, and THYM." (PMID 35274005, 2022). "On the contrary, LoVo‐FUBP1 with DVL1 overexpression xenografts recovered the tumor volume and tumorigenicity compared with LoVo‐shFUBP1 xenografts." (PMID 34288405, 2021). "In this study, we revealed that FUBP1 is relevant with tumor progression and metastasis in CRC tissues and cell lines." (PMID 34288405, 2021). "Further studies demonstrated that the nuclear localization of FUBP1 contributed to tumor immune evasion by regulating the expression of NRP1." (PMID 33987449, 2021). "Then, the tumor sphere formation assays were performed to inspect the influence of FUBP1 on the self‐renewal capability of spherogenic CRC cells." (PMID 34288405, 2021). "Meanwhile, high FUBP1 mRNA expression was strongly correlated with tumor progression and poor survival in CC patients." (PMID 33987449, 2021). "Taken together, Fubp1 likely functions as both a tumor suppressor and an oncogene and the detailed molecular mechanisms of Fubp1 in each context need to be determined." (PMID 32481602, 2020). "While, introduction of NORAD-4 fragment, which bound with FUBP1, successfully reversed tumor growth and apoptosis inhibition mediated by NORAD knockdown in vivo." (PMID 32555178, 2020). "Mounting evidence has collectively demonstrated both the oncogenic and tumor suppressive roles of Fubp1 and the debate regarding its roles in tumorigenesis has been around for several years." (PMID 32481602, 2020). "In the present study, we demonstrated the tumor-promoting function of Fubp1 by showing that Fubp1 transcriptionally activates cyclin A to promote cell cycle progression." (PMID 32481602, 2020). "The molecular mechanisms by which FUBP1 contributes to tumor propagation are currently being investigated." (PMID 32481602, 2020).
tumor (continued). "Although the Fubp1-cyclin A axis still needs to be verified in various types of tumors, our data suggest that Fubp1 has a tumor-promoting function by enhancing cell cycling." (PMID 32481602, 2020). "Several of the remaining 21 genes not in the GS, such as MYH14, MED23, and ZFP36L1 in BRCA, and ZNF292, FUBP1, and DTX1 in CLL, had also been implicated in tumor development." (PMID 29030609, 2017). "We found a significant correlation between the tumor size and stage and the levels of FUBP1 mRNA expression in ccRCC tissues from patients." (PMID 28076379, 2017). "Similar to the analysis comparing primary and recurrent tumors, the mutation status differed among tumor regions, even that of major driver genes such as CIC, FUBP1, PTEN, and NOTCH1." (PMID 28270234, 2017). "The biological function of FUBP1 during tumor cell proliferation was studied by MTS, colony formation, and soft-agar colony formation." (PMID 28076379, 2017). "In both biological systems, HSCs and FUBP1 (over-) expressing tumor cells, the FUBP1 transcription network provides pro-proliferative and antiapoptotic activity." (PMID 28588622, 2017). "FUBP1 is also involved in tumor initiation and progression by affecting several key cellular activities of tumor cells, such as apoptosis, proliferation and migration." (PMID 28076379, 2017). "The frequency of mutations identified at a higher frequency in our study (IDH1, CIC and FUBP1) are similar to those reported by others for this tumor type." (PMID 25694352, 2015). "Exome sequencing confirmed the IDH1 mutation and revealed novel mutations in FUBP1 and CIC in the primary tumor as well as the xenograft relative to the normal patient genome." (PMID 23527265, 2013). "Increased levels of PRMT5 and FUBP1 were detected in tumor tissues compared with adjacent tissues." (PMID 39146021, 2024). "Additionally, evidence suggests that FUBP1 can bind to non-coding RNAs and play a crucial role in tumor development." (PMID 38443680, 2024). "Collectively, these findings indicate that whether FUBP1 functions as an oncoprotein or tumor suppressor depends on the tumor type." (PMID 37180822, 2023). "However, the significant interaction p-value (0.016) between values and disease site indicates that anti-FUBP1 aAb level is a good prognostic marker when the tumor is in the tail body of the pancreas." (PMID 37910256, 2023). "Moreover, we found reduced FUBP1 methylation in tumor tissues with multiple probes, such as cg22814740 (p = 5.28e-05) and cg08491437 (p = 1.4e-06)." (PMID 35274005, 2022). "However, the expression of FUBP1 was much stronger in the tumor tissues than in the normal control tissues, which is consistent with the in silico study." (PMID 35274005, 2022). "IHC analysis revealed nuclear FUBP1 staining in both tumor and normal tissues." (PMID 35274005, 2022). "Interestingly, more than 50% of CIC and FUBP1 mutations were found to be subclonal in LGG samples, suggesting that they probably occurred late during cancer evolution and played roles in tumor progression." (PMID 35496054, 2022). "Whether increased FUBP1 was derived from tumor tissues and whether FUBP1 could be potential biomarker for CRC diagnosis needed to be further studied." (PMID 34917649, 2021). "Such stimulations on tumor sphere formation by FUBP1 were also observed in HCT116 and SW620 cells." (PMID 34288405, 2021). "Single‐stranded DNA‐binding protein, far upstream element‐binding protein 1 (FUBP1), is highly expressed in various tumor tissues, such as renal cell carcinoma, squamous cell carcinoma, liver cancer, gastric cancer, breast cancer, non–small‐lung cancer, and Hodgkin's lymphoma." (PMID 34288405, 2021). "Similarly, LoVo spheres sorted by tumor sphere formation also showed higher FUBP1 levels than the LoVo cells." (PMID 34288405, 2021). "Collectively, this study revealed that FUBP1 might be a potential therapeutic target for the restriction of tumor progression." (PMID 33987449, 2021).